RN7SKP44 (RN7SK pseudogene 44)
Gene: Miscellaneous RNA gene on chromosome 18 (31,718,893 to 31,719,208, forward strand). Ensembl gene ENSG00000200472.
Homologues: Orthologues: chimpanzee 7SK (88% identical). Paralogues in human: RN7SKP203 (77% identical), RN7SKP9 (76% identical), RN7SKP176 (75% identical), RN7SKP180 (74% identical), RN7SKP184 (74% identical), RN7SKP79 (74% identical), RN7SKP189 (74% identical), RN7SKP78 (74% identical), RN7SKP250 (73% identical), 7SK (73% identical), RN7SKP204 (73% identical), RN7SKP245 (73% identical), and 283 more.